JAK2 (Janus kinase 2)
Diseases named in the same sentence as JAK2 in open-access papers (continued):
Sharing a sentence is not in itself a finding about the gene and the disease.
tumor (continued). "Consequently, JAK–STAT activation, in a JAK1/JAK2- and STAT1/STAT3-dependent manner, is required for the transition to a stem-like, multilineage and EMT state but not for the tumor cells that have completely redifferentiated to an NE-like lineage." (PMID 36065066, 2022). "Despite the persistence of this positive predictive biomarker along with MSI, and the lack of aberrations in resistance genes (Janus kinase 2 [JAK2], phosphatase and tensin homolog [PTEN], serine/threonine kinase 11 [STK11]), the patient ended up with tumor progression on immunotherapy." (PMID 33608032, 2021). "However, the discontinuation of paclitaxel and momelotinib treatment no longer suppressed JAK2/STAT3 activation and CSC-like development, thus allowing the resumption of tumor growth and dissemination." (PMID 29682172, 2018). "JSI-124 treatment confirmed the contact-dependency of STAT3 activation, as we have previously demonstrated that this JAK2 inhibitor selectively blocks contact-dependent STAT3 activation but not that induced by soluble factors, such as IL-10 or tumor cells conditioned media." (PMID 24073274, 2013). "Similarly, deletion of Jak2 from mammary epithelial cells in general protected against tumor development in the MMTV-neu model, but deletion of Jak2 from tumor cells did not affect their proliferation." (PMID 23369183, 2013). "Solid Tumors: Although CuQ (0.5–1 mg/kg) inhibited tumor growth most effectively using A549 cells in a mouse xenograft model along with reduced p-STAT3 levels in a series of cancer cell lines, CuQ (10 μM) did not elicit a change in p-JAK2 (with contrasts with responses to CuA, CuB, CuE, and CuI)." (PMID 36355554, 2022).
cancer (810 papers, 2006 to 2026). A tumor composed of atypical neoplastic, often pleomorphic cells that invade other tissues. "Reduced OPN also diminished CD44 activation, impairing EMT-associated cancer stemness via JAK2/STAT3 and FAK/STAT3 pathways." (PMID 41356204, 2026). "The proinflammatory state characteristic of ET, particularly in JAK2 V617F-positive cases, is increasingly associated with elevated cancer risk." (PMID 40672006, 2025). "In summary, we can conclude that MCPIP1 and IL6 are directly linked and that both MCPIP1 and the IL6/JAK2/STAT3 pathway play essential roles in many cancers." (PMID 40874680, 2025). "Drug resistance in JAK2-associated cancers, particularly to JAK inhibitors like ruxolitinib, is a significant challenge in treating MPNs." (PMID 41226376, 2025). "Jak2 signaling, in particular, has been linked to the progression of certain cancer types, making it a promising target for therapeutic intervention." (PMID 40243485, 2025). "Network pharmacology identified 427 potential targets for 12 bioactive alkaloids, with core targets (PIK3CA, PIK3CD, MAPK8, and JAK2) implicated in cancer-related pathways such as PI3K-Akt signaling." (PMID 41169715, 2025). "Studies have shown that fibroblast activation protein (FAP), a derivative of cancer-associated fibroblast-like cells (CAFLCs), can activate the JAK2/STAT3 signaling pathway in GC." (PMID 40485724, 2025). "In the context of cancer, the JAK2/STAT3 signaling pathway is implicated in cell proliferation and survival." (PMID 40394236, 2025). "Its association with the JAK2 V617F mutation highlights its role in cancer susceptibility, while its impact on signaling pathways and the epigenetic landscape of cells contributes to the development of drug resistance." (PMID 41226376, 2025). "In contrast to JAK2-wild cancers, the TMB in JAK2-mutated cancers was remarkably greater in the discovery cohort (P = 0.0012) and within the verification cohort (P < 0.001)." (PMID 38200372, 2024). "We discovered that JAK2-mutated cancers displayed greater expression of proinflammatory chemotactic factors, which have been shown to attract CD8+ T cells, and their expression is increased when the JAK signaling pathway is activated." (PMID 38200372, 2024). "The immune system has been demonstrated to have an ability to effectively target cancer cells harboring the JAK2 V617F mutation, providing a basis for immune-based therapies specifically targeting JAK2 V617F as a new treatment approach." (PMID 39682299, 2024). "The expression of some costimulatory molecules was higher in JAK2-mutated cancers than in JAK2-wild cancers." (PMID 38200372, 2024). "Second, we compared the lymphocyte fraction (a vital population of white blood cells) between JAK2-wild cancers and JAK2-mutated cancers with the CIBERSORT approach using RNA-seq data." (PMID 38200372, 2024). "Next, we compared the TIL proportion, which was estimated by multiplying the estimated white blood cell proportion by the estimated lymphocyte proportion between JAK2-mutated and JAK2-wild cancers." (PMID 38200372, 2024). "First, we compared the white blood cell fraction between JAK2-wild cancers and JAK2-mutated cancers using DNA methylation array data and discovered that JAK2-mutated cancers contained a greater white blood cell fraction (P < 0.001)." (PMID 38200372, 2024). "Another report demonstrates that cancer-associated fibroblast-derived IL-6 increased c-Met expression in MET-unamplified GC cells through the IL-6/IL-6R/JAK2/STAT3 signalling pathway." (PMID 37950040, 2024). "We discovered that JAK2-mutated cancers displayed upregulated expression of immune checkpoint molecules (such as PDCD1, CD274, CTLA4, and TIGIT) compared with JAK2-wild tumors." (PMID 38200372, 2024). "This suggests that exosomal LINC00691 promoted NFs to gained the properties of cancer-associated fibroblasts (CAFs) depending on JAK2/STAT3 signaling pathway as a potential diagnostic biomarker for GC." (PMID 39703839, 2024).
cancer (continued). "We detected remarkably higher TCR (P = 0.043) and BCR richness (P = 0.019) in JAK2-mutated cancers than in JAK2-wild cancers." (PMID 38200372, 2024). "In particular, we discovered that JAK2-mutated cancers contained a remarkably greater proportion of immunostimulatory cells (CD8 T cells) (P < 0.001)." (PMID 38200372, 2024). "We found that JAK2 mutation independently and stably predicted the prognosis of patients with cancer who were treated with ICI therapy, and it is considered a promising biomarker to identify patients suitable for ICI therapy." (PMID 38200372, 2024). "Different earlier investigations revealed that the JAK-2 signaling pathway is linked to the development of cancer." (PMID 38827789, 2024). "The intrinsic immune responses of JAK2-mutated and JAK2-wild cancers were explored to elucidate the mechanisms underlying the prognostic significance of JAK2 mutations in the response to ICI treatment." (PMID 38200372, 2024). "Based on these results, JAK2-mutated cancers feature enhanced cancer immunogenicity and a relatively hot immune microenvironment, strongly supporting the prognostic significance of JAK2 mutation for determining the response to ICI treatment." (PMID 38200372, 2024). "According to the immune signature score estimated using ssGSEA, JAK2-mutated cancers were characterized by more immune cells, such as TILs (P = 0.007) and CD8+ T cells (P < 0.001)." (PMID 38200372, 2024). "Based on these results, we concluded that JAK2-mutated cancers contain more immune cells and exhibit greater TCR diversity, enabling them to recognize cancer antigens and induce more potent cancer-eliminating effects." (PMID 38200372, 2024). "JAK2/STAT3 signaling is aberrantly hyperactivated in various cancers, and such hyperactivation is commonly associated with a poor clinical prognosis." (PMID 36721234, 2023). "JAK2/STAT3 signaling activates epiregulin-induced cancer-associated fibroblasts, which stimulates the epithelial–mesenchymal transition (EMT) of OSCC cells, which is necessary for migration and invasion." (PMID 38259290, 2023). "STAT3 activation by IL-6 has been shown to regulate MSC-induced chemoresistance, and the blockage of STAT3 activation (with AG490, a JAK2 inhibitor) improved the susceptibility of cancer cells to chemotherapeutic agents." (PMID 35954425, 2022). "Previous studies generated JAK2V617F-specific CD8 T cell cultures from a healthy donor, which recognized and selectively killed JAK2-mutated cancer cells." (PMID 35603202, 2022). "The JAK2/STAT3 signaling pathway is involved in the progression of several cancers and is associated with other SOCS proteins through feedback regulation in various cell processes." (PMID 35126805, 2022). "This “compensatory” JAK2/STAT3 activation is considered as one of the main causes of drug resistance of cancer cells to MAPK pathway-targeted drugs." (PMID 36430869, 2022). "The aberrant activation of the JAK2/STAT3 signalling pathway has been observed in many types of cancer, and it is closely associated with tumorigenesis, cell proliferation, angiogenesis and the migration of cancer cells." (PMID 35068042, 2022). "For example, TGFB upregulation, CTNNB1 activation, and loss of PTEN and JAK2 reduce T cell priming and infiltration in cancer, leading to immune escape and immunotherapy resistance." (PMID 36119104, 2022). "Unexpectedly, the deletion of JAK2 can also be detected in some human cancers with a frequency comparable to that of its mutations." (PMID 35851582, 2022). "Constant activation of STAT3 and/or JAK2 are associated with cell proliferation in several cancers including breast, pancreatic, and lung." (PMID 33596259, 2021).
cancer (continued). "This transition is implicated in the regulation of metastasis and cancer progression and is driven by the IL-6/JAK2/STAT3 pathway in lung and ovarian carcinomas." (PMID 34207510, 2021). "The JAK2/STAT pathway is hyperactivated in many cancers, and such hyperactivation is associated with a poor clinical prognosis and drug resistance." (PMID 33795649, 2021). "Due to its high bioavailability, after oral administration, WP1066 binds specifically both to JAK2 and JAK2 V617F—the mutated form characteristic for cancer cells, thus inhibiting phosphorylation and kinase activation." (PMID 33158194, 2020). "In subgroup analyses, SVRRs were not significantly influenced by reason for prior ruxolitinib failure (relapsed/refractory or intolerant), number of prior anti‐cancer therapies, platelet count, hemoglobin level, patient age, or JAK2 mutational status." (PMID 32129512, 2020). "MoR-103a-2-3p, with high expression in the present study, was previously found very abundant in JAK2 mutated cancer cells, overexpressed in stem cells, and functionally linked to its flanking miRNA." (PMID 32143373, 2020). "It is confirming that the antiesophageal cancer effect of CT was associated with the inhibition of IL-6–mediated activation of JAK2/STAT3 signaling pathway." (PMID 32265690, 2020). "Constitutive activation of the JAK1/STAT3 pathway is frequently observed in cancer cells while JAK2/STAT3 is closely associated with cytokine expression, cell apoptosis, and proliferation." (PMID 32895373, 2020). "Dysregulation of JAK2/STAT3 signaling pathway is associated with many cancer progression and metastasis." (PMID 31754348, 2019). "In contrast, more immunogenic cancer cells with endogenous JAK2 deletion and BRAF or KRAS mutation (RKO and HCT116) displayed tolerance to momelotinib, reducing the combinatory effect." (PMID 30670049, 2019). "Previous reports have clarified that abnormalities in JAK2/STAT3 signaling are associated with oncogenesis in several types of cancer." (PMID 29242197, 2018). "The elevated leptin-led promotion of cancer progression is associated with the Janus kinase 2 (JAK)-signaling transducer and activator of transcription (STAT)-3 signaling pathway and STAT3 target gene expression." (PMID 28750624, 2017). "In this cancer context, JAK2 activation is implicated in the control of internalisation, but JAK2-STAT5 signalling does not require endocytosis." (PMID 28676702, 2017). "PKM2 is known to interact with a variety of biological molecules such as A-Raf, FGFR-1 and Jak-2 mutant and is also implicated in cancer metabolism." (PMID 23382852, 2013). "Several epidemiologic studies have investigated the association between the dysfunction of JAK2 and a variety of human diseases, including cancer." (PMID 23717640, 2013). "The strong association of JAK2 mutations with these cancers—as well as a wealth of preclinical validation—have led to the development of several JAK inhibitors, many of which are already in various stages of clinical testing." (PMID 22319590, 2012). "It has been suggested that the inhibition of JAK2/STAT3 underlies the apoptosis when cancer cells are treated with Cuc." (PMID 21304528, 2011). "Curcumin is known to inhibit several targets closely associated with cancer cell proliferation, in particular JAK2/STAT3 pathway." (PMID 20712901, 2010). "Identifying the 46/1 haplotype in patients may not only enhance risk stratification for Jak2-driven cancers but also guide more effective, personalized therapeutic strategies to overcome resistance." (PMID 41226376, 2025). "It has been suggested that genome alterations due to lowered or loss of CHEK2 and JAK2 expression may exacerbate cancer progression and predict poor patient survival." (PMID 40177144, 2025). "To conclude, identifying the 46/1 haplotype in patients may not only enhance risk stratification for JAK2-driven cancers but also guide more effective, personalized therapeutic strategies to overcome resistance." (PMID 41226376, 2025).
cancer (continued). "Moreover, based on the Danaher immune score, JAK2-mutated cancers contained more TILs (P < 0.001), CD8+ T cells (P = 0.004), and cytotoxic lymphocytes (P < 0.001)." (PMID 38200372, 2024). "Second, further physiological and pathophysiological experiments are required to confirm the correlations between JAK2 mutation and increased cancer immunogenicity and anticancer immunity, such as in vivo and in vitro experiments to explore the role of JAK2 in ICI treatment." (PMID 38200372, 2024). "The TIL fraction of JAK2-wild cancers was greater than that of JAK2-mutated cancers (P < 0.001)." (PMID 38200372, 2024). "The increased chemotactic factor expression in JAK2-mutated cancers was consistent with the finding of greater immunocyte infiltration in JAK2-mutated cancers, revealing that JAK2-wild tumors are capable of attracting immune cells to induce an extrinsic immune response." (PMID 38200372, 2024). "In summary, this study is the first to support the hypothesis that JAK2-mutated patients exhibit increased cancer immunogenicity and anticancer immunity, leading to an enhanced response to and long-term survival benefits of ICI therapy." (PMID 38200372, 2024). "Moreover, we utilized TCGA cohort multiomics data to investigate the differences in the immune landscape between JAK2-mutated and JAK2-wild cancers." (PMID 38200372, 2024). "Hence, we showed that JAK2-mutated cancers have greater immune cell infiltration than JAK2-wild cancers." (PMID 38200372, 2024). "In addition, immune signatures and Danaher immune scores were evidently enhanced in JAK2-mutated cancers compared to JAK2-wild cancers." (PMID 38200372, 2024). "We detected high lymphocyte fractions in JAK2-mutated cancers (P < 0.001)." (PMID 38200372, 2024). "In certain instances, the continuous activation of JAK 2 has been implicated in the survival, proliferation, angiogenesis, evasion of host immune responses, apoptosis resistance, and metastasis in various human cancers." (PMID 38127921, 2023). "Mutations in the gene Janus Kinase 2 (JAK2) are present in many forms of cancer." (PMID 37873786, 2023). "The mutation of JAK2 is related to many inflammatory diseases and malignant tumors." (PMID 36323529, 2023). "Furthermore, upon comparing the groups demonstrating alterations of CHEK2 and JAK2 (mutations and copy number variation, n = 703) with an unaltered group (n = 37045), several cancer-related genes were found to be preferentially altered in the former." (PMID 35851582, 2022). "Moreover, this vulnerability is uncoupled from JAK-inhibitor treatment, which is the standard-therapy for relevant subgroups of JAK2-mutated cancers." (PMID 35654819, 2022). "The upregulation, mutation, and amplification of JAK2 detected may participate in the invasion, migration, and proliferation of cancer cells in LUAD." (PMID 36733364, 2022). "In addition, with CuB, arrest of the G2-M phase and induction of apoptosis in cancer cells was associated with the inhibition of JAK2, STAT3, and STAT5 by decreasing Bcl-xL." (PMID 36355498, 2022). "However, it was also shown to be associated with growth and metastasis of cancer cells through inhibition of the function of natural killer cells and the interaction with the janus kinase 2 (JAK2)." (PMID 35389164, 2022). "Finally, development of specific pharmacologic KDM4C inhibitors will allow pre-clinical validation of demethylases as relevant clinical targets in JAK2-mutated cancers." (PMID 35654819, 2022). "JAK2 is a signaling molecule for cytokines; thus, when mutated, it may indicate a mechanism explaining altered immune surveillance in pediatric cancers." (PMID 36497424, 2022).